KMT2C (lysine methyltransferase 2C)
Diseases named in the same sentence as KMT2C in open-access papers (continued):
Sharing a sentence is not in itself a finding about the gene and the disease.
cancer (continued). "Unlike other COMPASS family members that trimethylated H3K4, MLL3 (KMT2C) and MLL4 catalyze histone H3K4 monomethylation at the enhancer and are the most common mutant histone modifiers in human cancer." (PMID 39165358, 2024). "A total of 136 nonsilent NSMs were identified in normal samples, with an average of 4.9, and 81 NSMs were identified in BPHs, with an average of 6.3, in the trio cases (p = 0.042), including the COSMIC cancer genes FOXA1, KMT2C, and BCOR." (PMID 38172600, 2024). "In contrast to KMT2A and KMT2B, KMT2C and KMT2D inhibit cell proliferation and are often considered tumor suppressors in different types of cancer." (PMID 38791111, 2024). "The most prevalent altered cancer-related genes were CTNNB1 (16%) and ZNRF3 (16%), followed by EGFR (11%), JARID2 (11%), KMT2B (11%), KMT2C (11%), NSD1 (11%), PIK3CA (11%), SH2B3 (11%), and UBR5 (11%)." (PMID 38023213, 2023). "In conclusion, these genetic findings highlight the importance of understanding the roles of BRAF, ARID2, KMT2C, and GNAQ in different cancer types, shedding light on potential therapeutic targets and predictive markers for cancer treatment strategies." (PMID 38023196, 2023). "We noticed that genes encoding chromatin modifiers were often hypermethylated in several cancer types, including the histone methyltransferases KMT2C (11 cancer types) and NSD1 (7 cancer types) and the histone demethylase KDM2B (6 cancer types)." (PMID 34871444, 2021). "Because of the strong correlation between these two epigenetic regulators and cancer developments, we first tested the mRNA expression levels of LSD1 and KMT2C after BJ-H-RasV12-ER and N4-H-RasV12-ER cells were treated with 4-HT." (PMID 31900384, 2020). "Interestingly, the distributions of several known cancer driver genes exhibit significant differences between cancer and normal tissues, such as FAT4, KMT2C, KMT2D, KRAS, PIK3CA, and PTEN." (PMID 39541191, 2024). "Mutations in MAATP53, EGFR, FAT4, KMT2C, ARID1A, FAT1, and RNF213 were observed in the original cancer tissues, whereas KRAS and BRAF mutations were not identified." (PMID 35721089, 2022). "Whether transcription factors mediating oncogenic programs in cancer cells, such as ELK1 downstream of the RAS/MAPK cascade, are responsible for KMT2C recruitment onto promoter regions is a hypothesis that warrants further investigation." (PMID 30665945, 2019). "KMT2C belongs to the family of histone-modifying proteins KMT2, it catalyses the monomethylation of H3K4 and recent studies provided significant data that bind dysregulation of genes coding chromatin-modifying and remodeling proteins to cancer." (PMID 30093974, 2018). "Conversely, perturbations that may promote aberrant stem cell-like activity and impair differentiation (cancer-promoting genes) included bromodomain-containing proteins (BRD1, BRD2), histone acetyltransferases (EP300), and histone lysine methyltransferases (KMT2C, NSD1, SETD1B)." (PMID 38472198, 2024). "Additionally, KMT2C decreased the expressions of EMT-related genes and cancer cell migration." (PMID 34885197, 2021).
cancer (continued). "Consistent with its role in the CD44 + / CD24− population, the knockdown of KMT2C significantly elevated the SFE of SKOV3 (P < 0.01), while the over expression of KMT2C significantly inhibited the SFE of TOV21G, indicating that KMT2C was directly related to the cancer stem cells (p < 0.01)." (PMID 32943985, 2020). "In addition, 1 SNP was detected in KMT2C, a BC oncogene, and 9 others were detected in or near 10 genes (SERAC1, DAGLB, MACF1, NVL, FBXW4, FANK1, KCTD4, CAVIN1; ATP6V0A1 and ZBTB20-AS1) previously associated with non-BC cancers." (PMID 35589867, 2022). "Co-occurring of genetic mutations in cancers with KDM5C alterations were not uncommon in both early-stage and advanced stage cohort and some of them are prevalent driver genes (e.g., LRP2, KMT2C, PBRM1, NOTCH1, FAT1, SETD2, NSD1, etc.), while their clinical significance remained undetermined." (PMID 33953726, 2021). "Interestingly, KMT2C, identified here as a potentially damaging gene and by the PCAWG as a candidate cancer driver, although not predicted to contain functionally impactful variants, showed the highest recurrence rate, irrespective of ancestry (7.1% European, 5.5% African)." (PMID 37444571, 2023). "Six of the 10 remaining genes, despite not being listed, were genes for which literature search supported undeniable oncogenic properties (STIM2, ARHGAP24, KLF12, KMT2C, CCDC88C and DOCK11), and 4 genes were—to our knowledge—not previously reported in cancer, yet may include new candidate drivers." (PMID 28534499, 2017).
tumor (194 papers, 2011 to 2026). "Clinically, KMT2C alteration has been linked to tumor mutational burden (TMB), microsatellite instability (MSI), immune infiltration patterns, and outcomes following immune checkpoint blockade (ICB)." (PMID 42292428, 2026). "Loss of KMT2C correlates with a reduction in proliferation in oestrogen-driven tumour cells but with a promotion of cell growth in oestrogen-depleted media." (PMID 36933062, 2023). "KMT2C (lysine-specific methyltransferase 2C) is a putative tumor suppressor that is frequently mutated in many malignancies and associated with tumor aggressiveness." (PMID 32351899, 2020). "ATRX and MLL3 (also known as KMT2C) were mutated in all regions in C3 except regions originating from tumour sample S2." (PMID 28916750, 2017). "Overall, 22.6% of tumours harboured a coding mutation in one of the seven Mut-driver genes involved in chromatin function (KMT2C, ARID1A, NCOR1, CTCF, KDM6A, PRBM1 and TBL1XR1)." (PMID 27161491, 2016). "The apparent loss-of-function alterations, including frameshift and nonsense mutations, suggest a tumor suppressor role for KMT2C and KMT2D." (PMID 24240169, 2013). "Moreover, we observed mutations in genes frequently associated with PC, such as SPOP, FOXA1, and KMT2C, in the tumor organoids." (PMID 40163511, 2025). "Loss of Kmt2c renders the Erbb2/Neu-driven tumours more responsive to lapatinib." (PMID 36933062, 2023). "In addition, 5 variants in two genes (HLA-A and KMT2C) were identified, which had pathogenic significance in other tumor types." (PMID 33075099, 2020). "The mutational pattern suggests a tumor suppressor function of KMT2C which may be disrupted by differently localized mutations." (PMID 32471474, 2020). "Additionally, it had six novel variants, five in HLA-A and one in KMT2C gene, implicated in other tumor types." (PMID 33075099, 2020). "Of note, truncating mutations in KDM6A, KMT2D, and KMT2C were frequently observed (74%; 14/19), suggesting that disruption of the epigenetic regulatory pathway may be involved in tumor development in urothelial BC." (PMID 32984035, 2020). "Also, 22 variants in five genes [ICOSLG, NCOR1, KMT2C, HLA-A and AR] were found to be pathogenic/ likely pathogenic in other tumor types." (PMID 33075099, 2020). "KMT2C is mutated in several epithelial cancers 8, implying a general role as a tumor suppressor." (PMID 30665945, 2019). "Eight tumor samples had two mutations, and two samples had four mutations in the KMT2C gene." (PMID 25537518, 2015). "KMT2C is mutated in a wide spectrum of neoplasms; it has been linked to tumorigenesis; and some studies suggest that variations in coding sequences of regulating elements, which act on enhancers to recognize specific transcriptional factors, may be the cause of tumor development." (PMID 39769419, 2024). "KMT2C loss may exert a dual impact depending on the tumor context." (PMID 37415738, 2023). "Additionally, KMT2C is one of the most frequently mutated genes in ER-positive breast cancer and its loss disrupts proliferation through estrogen and conversely promotes tumor outgrowth in hormone-depleted conditions." (PMID 35893033, 2022). "Thus, in tumor evolution, promoter methylation of KMT2C may provide a selective advantage to emerging KMT2C‐mutated cells by reducing wild‐type protein levels." (PMID 30665945, 2019). "Although KMT2C has been established as a tumour suppressor, the precise molecular mechanisms by which its deficiency drives metastasis and therapy resistance remain incompletely understood." (PMID 41674102, 2026). "Loss-of-function mutations in the Lysine Demethylase 6A (KDM6A), Lysine Methyltransferase 2C (KMT2C), and Zinc Finger MYM-Type Containing 3 (ZMYM3) are enriched in Group 4 tumors, indicating convergent epigenomic dysregulation in tumor development." (PMID 40867227, 2025). "Mutations in KMT2C disrupt this function, leading to abnormal H3K4 methylation levels, dysregulated gene expression, and malignant transformation of tumor cells." (PMID 40696688, 2025).
tumor (continued). "Third, we discovered that SCRN2 exerts its tumor‐suppressive functions by stabilizing the putative tumor suppressor KMT2C." (PMID 39836524, 2025). "KMT2D/KMT2C (Lysine Methyltransferase 2D/2C; MLL4/MLL3): Enhancer-modifying tumor suppressors whose loss rewires chromatin and can shape LUAD biology." (PMID 41154602, 2025). "In order to investigate the involvement of the KMT2C gene in tumorigenesis, we conducted an analysis utilizing data from XENA, TCGA, and GTEx databases to assess the transcriptional activity of KMT2C mRNA in both tumor and normal tissue." (PMID 38594266, 2024). "Deletion of the catalytic core of the SET structural domain in KMT2C induces cell hyperproliferation and uroepithelial tumor formation, but knockout of the entire gene is lethal in mice." (PMID 39165358, 2024). "In a PI3K-driven breast tumor model, KMT2C interacts with the FOXA1 transcription factor and mutational inactivation leads to increased mammary stem cell activity and accelerated tumor progression." (PMID 39165358, 2024). "In urothelial carcinoma, colorectal cancer, and acute myeloid leukemia, KMT2C has been shown to function as a tumor suppressor, although its role in tumorigenesis remains largely uncertain." (PMID 38791111, 2024). "Endothelial cells from Kmt2c KO and Kmt2d KO tumours were distinct from the WT and shared top upregulated genes, including Cd74, Cxcl9, H2-Ab1 and H2-Eb2." (PMID 38926506, 2024). "In our study, we investigated the tumor mutation landscape between the two subgroups and noted the top four mutated genes: TTN, PIK3CA, KMT2C, and MUC4." (PMID 38672263, 2024). "Quantitative RT-PCR analysis of tumour samples indicated minimal amounts of Kmt2c transcripts, possibly reflecting contaminating stromal cells." (PMID 36933062, 2023). "We reason that the mediators of MLL3 actions in tumor suppression should be within cluster 1 with reduced transcription and MLL3 binding in Kmt2c-deficient cells." (PMID 37261974, 2023). "Lysine methyltransferase 2C (KMT2C) is a tumor-suppressor gene in several myeloid cells and epithelia and is linked with blood and solid tumor cancers." (PMID 35409657, 2022). "To summarize, our findings indicate that KMT2A, KMT2C, KMT2D, and KMT2H are more likely to inhibit tumor occurrence, whereas other KMT2s are more likely to promote tumor occurrence and are generally associated with poor prognosis." (PMID 35058979, 2022). "Previous studies have shown evidence of tumour suppressive roles for KMT2C and its close paralogue KMT2D, and have proposed their involvement in cellular growth, stemness and epithelial differentiation." (PMID 35354467, 2022). "Lysine Methyltransferase 2C (KMT2C), also known as mixed-lineage leukemia 3 (MLL3), is a tumor-suppressor gene in several myeloid cells and epithelia." (PMID 35409657, 2022). "From the notable genetic aberrations identified in our patients, we have selected the KMT2C gene as a potential tumor suppressor inactivated in a significant proportion of patients." (PMID 35664801, 2022). "KMT2C is a tumor suppressor, and cells with low KMT2C activity lack homologous recombination-mediated double-strand break DNA repair, resulting in a significantly high rate of endogenous DNA damage and genomic instability." (PMID 34354750, 2021).
tumor (continued). "The WES analyses detected mutations in KMT2C, KNL1, and NCOR2 genes in all the tumor samples (100%)." (PMID 34245124, 2021). "Functional analysis confirms an oncogenic role for the ZMIZ genes, and tumor suppressive roles for KMT2C, CREBBP and NCOA2, in the initiation or progression of human cuSCC." (PMID 34398873, 2021). "The KMT2C protein, also known as MLL3, is part of a transcriptional coactivator complex and a tumor suppressor involved in several cellular processes, including the regulation of homeostasis and hormone receptor signaling." (PMID 33655698, 2021). "KMT2C regulates enhancer activation and assists tumor proliferation in a hormone-rich environment, possibly pointing to a role in ER + BC, especially in older cases." (PMID 33168853, 2020). "The KMT2C(MLL3)-KDM6A(UTX)-PRC2 regulatory axis modulates the expression of various downstream tumour suppressor genes, and thus the inactivation of KDM6A results in the activation of super-enhancers and contributes to the squamous subtype of PDAC in females." (PMID 33008426, 2020). "The general tendency for slower growth or decreased colony forming ability detected for the respective RKO and HCT116 derived KMT2CinsG KI cell lines was consistent with the suggested tumor suppressor role of KMT2C." (PMID 32471474, 2020). "Specifically, biallelic knockout of the SET domain of Kmt2c/Mll3 in mice led to formation of epithelial tumors, which supports a tumor suppressor role for the H3K4 monomethylase function of the gene." (PMID 32471474, 2020). "KMT2C is a well-established haploinsufficient tumor-suppressor gene localized on 7q and is frequently deleted in a hemizygous manner in AML patients." (PMID 33302406, 2020). "The lysine‐specific methyltransferase 2C (KMT2C/MLL3) is a putative tumor suppressor in several epithelia and in myeloid cells." (PMID 30665945, 2019). "In this report, we utilize tumor genome sequencing analyses to help uncover the H3K4 methyltransferase KMT2C as a critical regulator of hormone-dependent ERα activity." (PMID 29755131, 2018). "Beyond tumor-intrinsic effects, KMT2C dysfunction can reshape the tumor immune microenvironment through altered antigenic burden, inflammatory signaling, senescence-associated secretory programs, and dynamic stromal interactions, ultimately giving rise to heterogeneous therapeutic vulnerabilities." (PMID 42292428, 2026). "However, the regulation of GSK3b/p65, DSB repair and other signaling pathways by KMT2C needs to be further investigated, and the specific mechanism of KMT2C’s action in other tumors and its potential as a novel anti-tumor therapy need to be further studied." (PMID 39165358, 2024). "Three additional gene knockouts (Zbtb16, KMT2C, and Kmt2d) showed that the loss of KMT2C was essential to induce lung metastasis but not tumor progression." (PMID 39770431, 2024). "Additionally, genetic variants of KMT2C identified through WES have been reported to interfere with the process of opening chromatin in the DNA repair system, potentially leading to tumor development." (PMID 38256178, 2024). "Our results uncovered a bona fide tumour suppressor role for KMT2C in mammary tumorigenesis." (PMID 36933062, 2023).